CD36 (CD36 molecule (CD36 blood group))
Diseases named in the same sentence as CD36 in open-access papers (continued):
Sharing a sentence is not in itself a finding about the gene and the disease.
diabetes (continued). "Induction of diabetes in αMHCCre control mice increased zDHHC4 expression by 78% and increased CD36 S-acylation 1.8-fold." (PMID 40357580, 2025). "Collectively, these data demonstrate that CMA treatment in diabetes decreases CD36 S-acylation and localization at the sarcolemma, which improves dysregulated lipid metabolism and enhances cardiac function." (PMID 40357580, 2025). "Pharmacological inhibition of zDHHC enzymes in diabetic hearts decreased CD36 S-acylation, sarcolemmal CD36 content, FA oxidation rates and triglyceride storage, culminating in improved cardiac function in diabetes." (PMID 40357580, 2025). "In contrast, the well-characterized APT1 inhibitor ML348 upregulated CD36 S-acylation in control hearts, and this was sufficient to recapitulate the metabolic dysfunction of diabetes." (PMID 40357580, 2025). "According to the literature, CD36 exhibits a broad spectrum of expression and plays a crucial role in the pathophysiology of diabetes, as well as in the dietary selection of fatty foods." (PMID 40806099, 2025). "Understanding the molecular mechanism responsible for increased CD36 S-acylation is critical for identifying the drivers for metabolic dysfunction in diabetes." (PMID 40357580, 2025). "While TGR5 deletion did not affect CD36 palmitoylation under normal physiological conditions, TGR5ΔCM mice exhibited higher levels of CD36 palmitoylation than TGR5fl/fl mice in HFD/STZ-induced diabetes." (PMID 38698281, 2024). "In mid-stage diabetes, an increase in cell-cell interactions was found in the livers of diabetic mice primarily originating from aHSCs and Cd36+ KCs, as revealed by ligand-receptor pair analysis." (PMID 39494341, 2024). "More work is needed to definitively identify the mycobacterial component that elicits the activation of the CD36-PPARδ signaling axis, especially in the context of diabetes." (PMID 38989454, 2024). "While our study provides valuable insights into the intricate interplay between the CD36-PPARδ signaling axis in tuberculosis (TB), particularly in the context of diabetes, several limitations should be acknowledged." (PMID 38989454, 2024). "CD36 is an important component of the pathogenesis of diabetes mellitus and its complications due to the effects mediated by lipid transport, alterations in insulin response, and glucose metabolism." (PMID 40625574, 2023). "Overexpression of CD36 in the cardiomyocytes of diabetic db/db mice promotes CD36-mediated long-chain FA uptake and TG accumulation, inducing diabetes-mediated cardiac lipotoxicity and subsequent contractile dysfunction." (PMID 37009790, 2023). "Multivariate analysis showed that the plasma CD36+ MP level was a better biomarker of diabetes than the CD36 protein concentration." (PMID 40625574, 2023). "CD36 as a fatty acid transporter was reported to be involved in lipid induced M1 MQ polarization in diabetes." (PMID 37978397, 2023). "Increased CD36 expression was detected in the kidney cells of patients with diabetes and has been shown to contribute to DKD progression via palmitate-induced tubular apoptosis and tubulo-interstitial fibrosis." (PMID 37760019, 2023). "The recent study indicates that up-regulated nuclear micro-RNA (miR)-320 and down-regulated miR-200b-3p induced by diabetes directly promote CD36 transcription and translation, respectively, thus further promoting the sarcolemma distribution of CD36." (PMID 36187088, 2022). "SARS-CoV-2 virus particles were detected in the pancreas of patients with COVID-19, accompanied by altered expression of CD36 and other molecules potentially contributing to the pathogenesis of diabetes." (PMID 35343389, 2022). "To test the relevance of CD36 and diabetes-induced oxidative stress in vivo, we measured the level of urinary MDA and 8-OHdG by an ELISA." (PMID 34021126, 2021). "Variations in CD36 can lead to several conditions, such as sensory perception, diabetes, coronary heart disease, and others." (PMID 34648514, 2021).
diabetes (continued). "In the context of metabolic diseases such as diabetes and hyperlipidemia, CD36 has been suggested to be a key molecule to affect cardiac function." (PMID 34940639, 2021). "Although some studies demonstrated that induction of CD36 is accompanied by induction of PPARα in diabetic hearts, their induction levels vary a lot depending on various factors, including models of diabetes, used animals and the time course." (PMID 34940639, 2021). "The expression levels of CD36 are upregulated with its translocation to the sarcolemma in diabetes and hyperlipidemia." (PMID 34940639, 2021). "Here, we consider recent insights into how the CD36 response becomes deregulated under metabolic conditions, as well as the therapeutic benefits of CD36 inhibition, which may provide clues for developing strategies aimed at the treatment or prevention of diabetes associated with metabolic diseases." (PMID 34360006, 2021). "CD36 initiating redox signaling revealed the core pathophysiology of metabolic disorders such as diabetes, and promising therapeutic targets are expected." (PMID 34360006, 2021). "FAT/CD36 is highly expressed and upregulated in the presence of dietary fat, genetic obesity, and diabetes mellitus." (PMID 33920345, 2021). "It has been reported that myocardial CD36 expression/sarcolemmal translocation is increased under diseased conditions such as diabetes and hyperlipidemia." (PMID 34940639, 2021). "Another study revealed that there was an activation state of peripheral blood monocytes in diabetes with the increasing of CD36 and MCP-1 gene expressions." (PMID 34330221, 2021). "In conclusion, our results indicate that CD36-mediated FA uptake is required for sufficient energy supply to maintain contractile function in STZ-induced diabetes." (PMID 34940639, 2021). "CD36 was described nearly 30 years ago as “glycoprotein IV,” and increased synthesis of the CD36 protein has been observed in people with diabetes." (PMID 32626782, 2020). "For these reasons, CD36 has been proposed as a biomarker of future cardiovascular disease in diabetes with potential clinical applicability." (PMID 32498389, 2020). "Our results indicate that CD36 signaling is partially involved in hyperglycemia and oxLDL-induced vascular calcification in diabetes." (PMID 33028031, 2020). "Gene expression of the fatty acid transporter Cd36 in the LV was significantly increased overall by diabetes (P = 0.034) and at 8 weeks of diabetes." (PMID 32153425, 2020). "CD36 responsiveness to metabolic abnormalities presents a challenge to its use as a marker of pioglitazone target engagement in diseases such as diabetes." (PMID 31910209, 2020). "Altogether, our results indicate that CD36 and ER stress are potential therapeutic targets to alleviate vascular calcification in diabetes." (PMID 33028031, 2020). "Except for the influence of diabetes on Cd36, Scl27a5/Fatp5 and Slc27a6/Fatp6 at E18.5, the effects of diet on fatty acid transporter expression levels were normalized towards the end of pregnancy." (PMID 31774824, 2019). "Gene expression of other insulin-responsive metabolic enzymes, including transcription factors Forkhead Box O1 and O6 (FoxO1, 6) and the fatty acid transporter, CD36, and fatty acid synthase were both modulated by diabetes but were unaffected by SRT3025." (PMID 30228292, 2018). "In conclusion, STAMP2 gene overexpression significantly downregulated the angiogenesis of EWAT and BAT via the PPARγ/CD36 signalling pathway, contributing to the improvement of IR and providing a new treatment target for diabetes and related diseases." (PMID 28631352, 2017). "Taking glycated CD36 as a dependent variable, the results showed that CD36 expression was related to only diabetes, which was related with glycated CD36 (β = 0.46, p = 0.03)." (PMID 28729885, 2017).
diabetes (continued). "In the present study, we found that, in the late stage (8 weeks of diabetes) of STZ-induced diabetes, rats displayed the inactivation of STAT3, APN deficiency, and the increase of FoxO1 and CD36 expression." (PMID 26783539, 2016). "In summary, this study demonstrated that, in the late stage of STZ-induced diabetes, rats displayed the inactivation of STAT3, APN deficiency, and the increase of FoxO1 and CD36 expression." (PMID 26783539, 2016). "The high expressions of FoxO1 and CD36 in diabetic groups displayed an aggravating cardiac injury and suggested the correlation between FoxO1, CD36, and lipid metabolism disorder in diabetes." (PMID 26783539, 2016). "Diabetes showed reduction of cardiac STAT3 activation (p-STAT3) and adiponectin with concomitantly increase of FoxO1 and CD36, which associated with reduced sevo-postC cardioprotection." (PMID 26783539, 2016). "Our study also indicated that the treatment of chelerythrine downregulated CD36 and IL-1β as well as inflammation related genes like IFNγ and TNFα, which are of great benefits for the treatment of diabetes." (PMID 26183621, 2015). "At 4 months after diabetes onset, cardiac CD36 expression in FGF21KO diabetic mice was significantly higher than that of WT diabetic mice." (PMID 25823710, 2015). "The redistribution of FAT/CD36 to the sarcolemma is one of the earliest alterations occurring in the heart during diet-induced diabetes, and has been observed in ZDF rats and in STZ mice in proportion to the severity of insulin deficiency." (PMID 25856422, 2015). "Multivariate analysis confirmed that plasma CD36+MP levels were a much better biomarker for diabetes than CD36 protein concentration (p=0.009 vs. p=0.398, respectively)." (PMID 26082317, 2013). "It has been shown that CD36 membrane levels and turnover are abnormal in diabetes, resulting in dysfunctional fatty acid utilization." (PMID 26029481, 2013). "This balance between FAT/CD36 and GLUT4 has been noted in animal models, as in diabetes or following a lipid infusion the expression of FAT/CD36 increases and GLUT4 decreases." (PMID 22028857, 2011). "We selected the Cd36 gene related to diabetes for the subsequent research." (PMID 41584930, 2026). "Inducing diabetes in the FoxO1-deficient littermates (Foxo1Cardiac−/−) prevented this response, with no significant increase in zDHHC4 expression or CD36 S-acylation relative to controls in response to diabetes." (PMID 40357580, 2025). "To determine whether increased CD36 S-acylation contributes to cardiac metabolic and contractile dysfunction in diabetes, we infused the zDHHC inhibitor CMA into diabetic hearts." (PMID 40357580, 2025). "Post-translational S-acylation controls protein trafficking, and in this study we hypothesised that increased CD36 S-acylation may underpin the preferential sarcolemmal localisation of CD36, driving metabolic and contractile dysfunction in diabetes." (PMID 40357580, 2025). "Using a combination of rodent, pig, and human tissues in combination with genetic and pharmacological in vivo and ex vivo approaches, we demonstrate increased CD36 S-acylation in diabetes, which is conserved between species and is sufficient to drive metabolic and contractile dysfunction." (PMID 40357580, 2025). "From a molecular standpoint, hyperglycemia may activate PPAR-γ, promoting CD36 overexpression in macrophages and accelerating atherogenesis in diabetes." (PMID 40867895, 2025). "We next investigated the mechanism driving increased CD36 S-acylation in diabetes." (PMID 40357580, 2025). "Diabetes-induced downregulation of APT1 redirects palmitoylated CD36 into the recycling pathway." (PMID 40607256, 2025). "This study sets out to investigate if the S-acylation of CD36 is a driving force for metabolic and contractile dysfunction in the diabetic heart and, critically, if pharmacologically targeting the S-acylation enzymes can reverse dysfunction in diabetes." (PMID 40357580, 2025).
diabetes (continued). "CD36 is a scavenger receptor that functions in lipid metabolism and has been reported to be involved in inflammatory responses and metabolic disorders, such as diabetes and obesity." (PMID 36878933, 2023). "In conclusion, we identified differential roles of CD36 in regulating muscle insulin response under conditions with and without PA overload, which provides supportive evidence for further research into therapeutic approaches to diabetes." (PMID 36979708, 2023). "Importantly, treatment with SGLT2i uniformly enhanced glucose oxidation in the various tissues, and it decreased expression of hepatic CD36, suggesting that, in diabetes, SGLT2i shift TCA cycle metabolism from fatty acid to glucose oxidation." (PMID 36809274, 2023). "We found that platelet CD36 level was significantly increased in overweight patients with NVAF independent of well-known risk factors, such as hypertension, coronary artery disease, heart failure, and diabetes mellitus." (PMID 36465448, 2022). "As a consequence of its functions, CD36 might be associated with a wide range of disorders such as CVD, dyslipidemia, hypertension, diabetes, metabolic syndrome, and cancer." (PMID 35396566, 2022). "The combination of CD36 gene polymorphisms with CD36 gene methylation had no impact on the plasma sCD36 level in the control group or the diabetes group." (PMID 36031603, 2022). "However, several aspects such as obesity, diabetes, Single Nucleotide polymorphisms (SNPs), and oxidative stress affect the normal FAs metabolism and function of FAT/CD36, inducing metabolic disease." (PMID 36615118, 2022). "Many molecules are involved in islet function and the pathogenesis of diabetes, including CD36, glucose transporters (GLUT) 2, insulin receptor substrate (IRS) 1, IRS2, pancreatic and duodenal homeobox 1 (PDX1), and peroxisome proliferator activated receptor gamma (PPARG)." (PMID 35343389, 2022). "The up-regulation of CD36 has been evidenced on the sarcolemma of cardiomyocytes in diabetic mice and patients with DCM, which is owing to both high membrane translocation and high expression of CD36 triggered by hyperinsulinemia, hyperglycemia and hyperlipidemia during the development of diabetes." (PMID 36187088, 2022). "Emerging evidence has shown that triacylglycerol accumulation within the myocardium may be responsible for the development of diabetes-induced heart failure, and this process is mainly modulated by transport protein fatty acid translocase CD36." (PMID 34764865, 2021). "CD36 expression levels are higher in CKD subjects with diabetic nephropathy and kidney damage and are closely associated with CV risk factors such as hyperlipidemia and diabetes." (PMID 34629330, 2021). "A case-control study was conducted and included 177 patients with type-2 diabetes mellitus (T2DM) and 173 control subjects to study the involvement of CD36 gene rs1761667 (G>A) and rs1527483 (C>T) polymorphisms in the pathogenesis of T2DM and dyslipidemia among Jordanian population." (PMID 34648514, 2021). "Most importantly, the present study suggests that CD36 and ER stress could be potential targets for novel therapeutic strategies to alleviate vascular calcification in subjects with diabetes." (PMID 33028031, 2020). "We measured gene and protein expression of CD36 by real-time PCR, immunohistochemistry, and Western blot, respectively, and observed that it was markedly increased in plaque tissue from subjects with diabetes." (PMID 33028031, 2020). "In addition, we found that CD36 expression was exacerbated in carotid plaques from subjects with diabetes compared with carotid plaques from normoglycemic subjects." (PMID 33028031, 2020). "LV Nox2 and Cd36 expression were elevated after 16 weeks of diabetes." (PMID 32153425, 2020).
diabetes (continued). "Hormone-sensitive lipase, which is activated in diabetes, lipoprotein lipase, which is often defective in diabetes, and the fatty acid transporter Cd36, which is involved in the FFA uptake, are regarded as main contributors of plasma levels of FFA and triglycerides." (PMID 30286142, 2018). "We found decreased Cd36 mRNA in the diabetes-exposed Hif1a+/− offspring compared to other groups." (PMID 29753320, 2018). "However, this condition can inhibit glycated CD36 protein expression, as has been found in patients with poorly-controlled diabetes in another study carried out by our group." (PMID 28729885, 2017). "NAC and sevo-postC confer synergy in reducing myocardial IRI in diabetes and the possible mechanism may be associated with the increased expression of p-STAT3, APN restoration, and the decreased expression of Fox1 and CD36 in diabetic rats." (PMID 26783539, 2016). "At 3 months, fructose feeding induced upregulation of several genes coding nuclear factors (Rxrg, Nr1h3, p≤0.1), proteins involved in lipid metabolism including Pltp (p≤0.1), Lcat, and Cd36 (p≤0.05), cell death inflammation (Tnf, p≤0.1), and diabetes (Irs1, Slc2a2, p≤0.1)." (PMID 25380250, 2014). "Therefore, CD36 expression on the surface of monocytes and macrophages is up-regulated by oxLDL in patients with type 2 diabetes mellitus (DM)." (PMID 24016701, 2013). "The regulation of CD36 by Stat1 may be important in other pathophysiological events involving CD36-dependent lipid uptake and inflammation, such as diabetes mellitus and the metabolic syndrome." (PMID 20011528, 2009). "Perhaps, in compensation, collagen receptor CD36 becomes highly expressed in both diabetes types." (PMID 18177501, 2008). "Hyperglycemia-induced synthesis of CD36 protein in macrophages has been associated with increased uptake of ox-LDL by macrophages and foam cell formation in atherosclerotic lesions in people with diabetes." (PMID 15737001, 2005). "These in vivo findings demonstrate a strong association of diabetes-induced CD36 expression and apoptosis in PTECs in human DNP, suggesting that CD36 may play a critical role in TED by mediating PTEC apoptosis in progressive human DNP." (PMID 15737001, 2005). "However, whether APT1 contributes to diabetes-induced podocyte lipotoxicity by affecting the posttranscriptional regulation of CD36 remains unclear." (PMID 40607256, 2025). "At last, this study also indicated that genetic screening of CD36 variants could be helpful for early intervention or prevention of EOCAD in individuals with high risk factors (e.g., smoking, hypertension, diabetes, and family history of atherosclerotic cardiovascular disease)." (PMID 40040886, 2025). "Diabetes was associated with a 6-fold increase in the expression of the fatty acid transporter CD36 in the liver but not in the kidney or heart (not shown), suggesting that increased fatty acid uptake by the liver induces energy production under conditions of restrained glucose oxidation." (PMID 36809274, 2023). "The effects of LDL-cholesterol and activation of CD36/oxidised LDL receptor warrant further investigation, as it has been shown that CD36 mediates multiple pathways associated with the early pathogenesis and progression of diabetes-related complications in general." (PMID 35852586, 2022). "The cluster of differentiation 36 (CD36) is a scavenger receptor present on various types of cells and has multiple biological functions that may be important in inflammation and in the pathogenesis of metabolic diseases, including diabetes." (PMID 34360006, 2021). "Second, CD36 is expressed in many cells sensitive to metabolic abnormalities related to metabolic syndrome, prediabetes, and DM." (PMID 32796572, 2020).